VEGFA (vascular endothelial growth factor A)
Diseases named in the same sentence as VEGFA in open-access papers (continued):
Sharing a sentence is not in itself a finding about the gene and the disease.
lung adenocarcinoma (140 papers, 2005 to 2026). A carcinoma that arises from the lung and is characterized by the presence of malignant glandular epithelial cells. "It has been shown that cancer-associated fibroblasts (CAFs) isolated from murine lung adenocarcinomas secreted abundant VEGFA and enhanced tumor cell invasion in coculture studies." (PMID 25003366, 2014). "VEGFA mRNA expression was significantly elevated in lung adenocarcinoma tissues compared to adjacent normal tissues." (PMID 40940965, 2025). "Meanwhile, we further verified the role that SLC2A1 mediates VEGFA secretion in lung adenocarcinoma tissues." (PMID 38390340, 2024). "For instance, LUCAT1 facilitates glycolysis and metastasis of lung adenocarcinoma cells by functioning as a competing endogenous RNA that regulates the miR-4316/VEGFA axis." (PMID 39167430, 2024). "This improvement is likely due to the observed increase in VEGFA expression among PD-L1-positive lung adenocarcinomas, a phenomenon also noted in various other cancers." (PMID 39161896, 2024). "LncRNA-UCA1 interacts with miR-383, which in turn enhances VEGFA's expression in lung adenocarcinoma." (PMID 38687357, 2024). "In the validation set, VEGFA, TIMP1 and SPP1 were still found to be significantly associated with the survival of lung adenocarcinoma patients." (PMID 37189418, 2023). "Next, a survival analysis of the validated ligands revealed that the high expression ligand signals VEGFA, TIMP1, and SPP1 were significantly associated with a lower chance of survival in patients with lung adenocarcinoma." (PMID 37189418, 2023). "Studies in lung adenocarcinoma patients revealed that elevated levels of VEGFA and Ang-2 is valued prognostic biomarkers and double targeting of VEGFA and Ang-2 can improve therapeutic outcome." (PMID 35392964, 2022). "Studies have found that LUCAT1 can promote the metastasis of lung adenocarcinoma cells and glycolysis by regulating the miR-4316/VEGFA axis." (PMID 36401283, 2022). "Upregulation of VEGFA also indicates a poor prognosis for lung adenocarcinoma and oral squamous cell carcinoma, suggesting that VEGFA represents a valuable prognostic biomarker." (PMID 34217310, 2021). "lncRNA LOC100132354 has been demonstrated to promote the proliferation and migration of vascular endothelial cells by upregulating VEGFA/VEGFR2 expression in lung adenocarcinoma, which further contributed to the tumorigenesis of lung adenocarcinoma." (PMID 32473645, 2020). "Accordingly, IL-17A and VEGF serum levels in patients with lung adenocarcinoma were positively correlated, and in tumoral cell lines, IL-17A induced VEGFA expression." (PMID 32987705, 2020). "As VEGFA is one of the hypoxia induced genes, the concentration of VEGFA in the serum of lung adenocarcinoma patients was examined by ELISA (22 in 27 blood samples for the study of serum concentration of CCL28)." (PMID 27250766, 2016). "We demonstrate enhanced transcription of the gene VEGFA (vascular endothelial growth factor A) with decreasing oxygen levels in human lung adenocarcinoma cells." (PMID 26360882, 2015). "In addition, it has been shown that antiangiogenic therapy targeting the components of the VEGFA/VEGFR2 pathway was effective in the treatment of lung adenocarcinoma (LAC), but biomarkers are required to identify the target group of patients." (PMID 39940785, 2025). "We examined the expression levels of SLC2A1 and VEGFA in the tumor tissues of 18 lung adenocarcinoma patients by immunohistochemical staining, and the IHC results showed that high expression of SLC2A1 was significantly correlated with the increased secretion of VEGFA." (PMID 38390340, 2024). "In summary, this study demonstrates that the TKI Nintedanib, an anti-VEGFA/Ang2 nanobody, but to a lesser extend also unspecific IgG can reduce BM formation, making blood vessel stabilization an attractive mechanism of BM prevention in lung adenocarcinoma." (PMID 32918638, 2020).
lung adenocarcinoma (continued). "A plethora of research studies identified that lncRNAs could target VEGFA in cancers such as lung adenocarcinoma and endometrial carcinoma." (PMID 32983957, 2020). "Co-expression of PD-L1 and VEGFA may be considered as an important prognostic factor for patients with resected lung adenocarcinoma." (PMID 30972298, 2019). "As a result, CCL28 could promote angiogenesis in lung adenocarcinoma and bypass the effects of VEGFA." (PMID 27250766, 2016). "Overall, VEGFA-, TIMP1, and SPP1-mediated regulatory networks may not only be the main cause of macrophage changes, but also these three signals may be markers of malignant changes in lung adenocarcinoma." (PMID 37189418, 2023). "For example, miR-29c has a binding site in the 3' UTR of VEGFA mRNA and can down-regulate the expression level of VEGFA, thereby promoting the capability of tumor cells to induce tube formation of human umbilical vein endothelial cells (HUVECs) in lung adenocarcinoma (LUAD)." (PMID 35918758, 2022). "Moreover, miR-29 c targets VEGFA to inhibit tumor angiogenesis of lung adenocarcinoma." (PMID 33564307, 2021). "Bioinformatics analysis confirmed elevated VEGFA and VEGFB mRNA expression in lung adenocarcinoma patients compared to healthy individuals." (PMID 42015273, 2026). "PLK1 inhibition suppresses the migration of A549 lung adenocarcinoma cells by decreasing MMP2 and VEGFA expression." (PMID 38355643, 2024). "Important regulatory molecules (VEGFA, TIMP1, SPP1, etc.)of macrophages in lung adenocarcinoma were identified by the gene regulatory network method." (PMID 37189418, 2023). "In lung adenocarcinoma, single-cell sequencing identified a macrophage population overexpressing SPP1 and VEGFA." (PMID 36569953, 2022). "Correlation analysis results showed that the expression of VEGFA, EGFR, CASP3, and AKT1 correlated with the median survival time of lung adenocarcinoma patients (P < 0.05)." (PMID 32148531, 2020). "Our studies have shown that the hub genes, such as VEGFA, EGFR, CASP3, and AKT1, as potential therapeutic targets of cinobufotalin injection correlated with the survival time of lung adenocarcinoma patients." (PMID 32148531, 2020). "In lung adenocarcinoma, TRIM11 promotes tumor angiogenesis through activating transcription 3 (STAT3)/vascular endothelial growth factor A (VEGFA) pathway." (PMID 31820796, 2019). "By staining paraffin sections of lung adenocarcinoma, we found that the VECs with PD-L1 overexpression simultaneously revealed higher expression of VEGFA, HIF-1α, and microvascular density compared with negative group." (PMID 32366856, 2020). "Targeting VEGFA, TIMP1, and SPP1 may be a potential therapeutic strategy for lung adenocarcinoma." (PMID 37189418, 2023).
depression (137 papers, 2009 to 2026). "Proteinsencoded by the TNFA, CASP8, TNR5, and VEGFA genes,which are associated with epilepsy, depression, and otherneuropsychiatric diseases, were found among regulators ofASM activity and transport." (PMID 38223851, 2023). "Intriguingly, 4 different down-regulated miRNAs all target the same validated growth factor, VEGFA (mir-20b, 20a, 34a, 34b*), a molecule implicated in depression in both humans and animal models (see Discussion)." (PMID 22427989, 2012). "We measured protein levels of several selected target proteins implicated in depression (DMNT3b, VEGFA, and BCL2) in all individuals by Western blotting (normalizing values using beta-acting immunoreactivity)." (PMID 22427989, 2012). "Interestingly, VEGFA is also a risk factor for depression and can be utilized as a prognostic factor for the development of recurrent depression." (PMID 38977982, 2024). "VEGFA is of interest as it is implicated in depression and can use the MAP kinase pathway." (PMID 33589676, 2021). "VEGFA is a growth factor implicated in depression in both humans and animal models." (PMID 22427989, 2012). "Another study found increased mRNA levels of VEGFA in peripheral blood cells and serum in patients with recurrent depression as compared to healthy controls, and suggested that VEGFA gene polymorphism could be a prognostic factor for the development of recurrent depression." (PMID 38297317, 2024). "One example is the vascular endothelial growth factor A (VEGF-A) which is typically higher in depression outside the perinatal period but has been found to be lower in APD, and in PPD compared with persistent depression." (PMID 40473930, 2025). "Among these core targets, SIRT1, HIF1A, ESR1, VEGFA, HSP90AA1 and PTGS2 are well documented to be associated with depression." (PMID 36496991, 2022). "There is a report shows that miR-27a plays key roles in depression through regulating vascular endothelial growth factor A (VEGFA)." (PMID 36040555, 2022). "Lastly, it has been found that higher circulant levels of VEGFA in major depression and its alterations are related to impaired cognitive function in schizophrenia." (PMID 35625687, 2022). "Basic studies demonstrated that modified BXXXD, a formula similar to GJHQHLRSD, can effectively alleviate UC as well as relieve depression and UC through targeting VEGFA, TNF, STAT3, EGFR, and others." (PMID 34539797, 2021). "Previous studies found that the expression levels of VEGFA in rats with chronic unpredictable mild stress-induced depression were significantly lower than those in the blank group." (PMID 34257681, 2021). "Cui measured the VEGFA mRNA and protein in hippocampus tissues and sera from a rat model of depression and found that they were downregulated in hippocampi and blood of the depressed rats." (PMID 33960267, 2021). "For a transcription gene linked to multiple levels of cellular regulation and metabolism, we included VEGFA, previously shown to differ in patients with major depressive disorder (MDD) compared to controls." (PMID 24826212, 2014). "Among targets that have been experimentally validated and that are co-expressed in prefrontal cortex, at least three (VEGFA, BCL2, and DNA methyltransferase 3B) have been previously implicated in depression or suicide." (PMID 22427989, 2012). "Also, its targets, such as DNA-methyltransferase 3 beta, Bcl2, and vascular endothelial growth factor-A (VEGF-A), changed, all of which were previously implicated in depression." (PMID 36457043, 2022). "In a previous study, serum VEGFA mRNA and protein levels were significantly elevated in patients with MDD, suggesting a potentially important role in the pathogenesis of depression." (PMID 38297317, 2024). "Studies have shown that AKT1, VEGFA, ESR1, IL6, and AR play an important role in the treatment of depression." (PMID 34257681, 2021).
depression (continued). "PPI network analysis showed that VEGFA, EGFR, CASP3, IL6, ESR1, and other targets have important implications in the treatment of depression with XPJYD." (PMID 34257681, 2021). "Our results also showed low VEGFA expression in the tumor group, suggesting a new avenue for the pathology and treatment of HCC complicated by depression." (PMID 33960267, 2021). "Our previous study also identified VEGFA as a target of miRNA in the MDD brain, revealing how miRNA expression changes in depression and suicide may influence VEGFA and related neuro-epigenetic pathways." (PMID 39645539, 2025). "Studies have shown that XPJYD improved the serum VEGFA concentration, regulated the PI3K/Akt/eNOS-specific pathway, regulated cerebral cortex blood flow, and improved depression symptoms in rats with chronic unpredictable mild stress-induced depression." (PMID 34257681, 2021). "The key targets of Epicedium for treating depression were IL6, VEGFA, AKT1, and EGF." (PMID 34479552, 2021).
brain tumors (136 papers, 2006 to 2025). "VEGFA is involved in promoting tumor-induced angiogenesis and implicated with brain tumor progression." (PMID 31952211, 2020). "The VEGFA mRNA expression levels in rhGDF15-stimulated U373 cells were confirmed using qRT-PCR before stereotactically injecting the cells into the brain tumors." (PMID 35280749, 2022). "However, significant differences were observed compared to healthy donors, confirming that brain tumor patients release more VEGFA into the bloodstream." (PMID 32564774, 2020). "We have previously shown that VEGFa is a prognostic marker in brain tumor patients." (PMID 28055976, 2017). "We asked whether VEGFA-regulated vascular leakage has an impact on the growth and vascular permeability of brain tumours." (PMID 27005951, 2016). "The results we show here highlights the importance of hypoxic mechanism in brain tumours and the high level of overexpression of angiogenic factors as HIF1A, VEGFA, and MMP2 that are implicated in metastasis could be target molecules in those tumour types." (PMID 22570651, 2012). "Correspondingly, IHC analysis of the removed mouse brain tumor sections confirmed the high expression of FBXO22, HIF-1α and VEGFA and low expression of VHL in the U87-FBXO22 group compared with the U87-Vector group." (PMID 38519492, 2024). "Importantly, multivariate Cox regression analysis showed that VEGFa expression and CD133 expression were independent prognostic markers in patients with brain tumors." (PMID 28055976, 2017).
retinal detachment (133 papers, 2010 to 2026). An eye emergency condition which may lead to blindness if left untreated. "The necessity of repeated intraocular injections for the administration of current anti-VEGFA therapy reduces patient compliance and results in rare but serious instances of eye damage caused by the injection procedure, such as endophthalmitis or retinal detachment." (PMID 32312382, 2020). "Dysregulation of vascular endothelial growth factor-A (VEGF-A) has been implicated in pathological retinal angiogenesis in these conditions, leading to edema, abnormal bleeding, and eventual retinal detachment, with no definitive treatment." (PMID 34285351, 2022).
rheumatoid arthritis (132 papers, 2004 to 2025). A chronic, systemic autoimmune disorder characterized by inflammation in the synovial membranes and articular surfaces. "It is worth mentioning that VEGFA is also significantly associated with other autoimmune diseases such as rheumatoid arthritis." (PMID 34557547, 2021). "Additionally, VEGFA was implicated in the Rheumatoid arthritis process, while FOSL2 was associated with Osteoclast differentiation." (PMID 40997129, 2025). "Similarly, we selected 9 nsSNPS that would be of prime significance in VEGFA association analysis with Rheumatoid Arthritis." (PMID 38081836, 2023). "VEGFA has been observed to be overexpressed in chronic inflammation, such as in cases of chronic intestinal diseases and rheumatoid arthritis." (PMID 41150107, 2025). "Along with TNF-α, vascular endothelial growth factor-A (VEGF-A) protein is increased in the serum of rheumatoid arthritis patients." (PMID 29548992, 2018). "Furthermore, several genes that were annotated in studies on rheumatoid arthritis (VEGFA, TGFB2, MMP1, MMP3, IL8, CCL3L1, CTSL1, CCL2) were also significantly upregulated in the immature articular cartilage in our study." (PMID 27045355, 2016). "The KEGG pathway of the CXC chemokine-VEGFA network in COAD was mainly involved in cytokine-cytokine receptor interaction, rheumatoid arthritis, interleukin- (IL-) 17 signaling pathway, and nuclear factor kappa B (NF-κB) signaling pathway." (PMID 36246978, 2022).
endophthalmitis (130 papers, 2009 to 2026). An infectious process affecting the internal structures of the eye. "There is a reported upregulation of vascular endothelial growth factor A (VEGF-A) in exogenous endophthalmitis, which promotes further blood–retinal barrier breakdown and exposes the tissues to injury by immune defense mechanisms." (PMID 38543107, 2024).
coronary artery disease (129 papers, 2008 to 2026). "Another meta-analysis demonstrated that VEGFA rs699947 C>A, rs3025039 C>T, and rs2010963 G>C polymorphisms are risk factors for coronary heart disease." (PMID 38089766, 2023). "A VEGFA polymorphism associated with higher VEGFA expression was found to be associated with a lower risk of coronary artery disease in an epidemiological study." (PMID 34260629, 2021). "Overall, the additive effects of VEGFA modRNA, bFGF modRNA and hADSCs hold promise for comprehensive cardiac repair post‐MI and show substantial potential for treating ischemic heart diseases." (PMID 40008489, 2025). "CircRNAs have been shown to influence different diseases such as coronary artery diseases and cancers by regulating VEGFA levels via binding to miRNAs." (PMID 37234708, 2023). "VEGFA is an angiogenic cytokine that promotes angiogenesis in the treatment of ischemic heart disease." (PMID 35600966, 2022). "This study explored the interrelationships among vascular endothelial growth factor A (VEGF-A), microRNA-210 (miR-210), and EphrinA3 in the plasma of patients with coronary heart disease (CHD), and their collective influence on coronary collateral circulation (CCC) development." (PMID 40717103, 2025). "Additionally, it has been demonstrated that GPR4 facilitates EPC-induced angiogenesis by activating the signal transducer and activator of transcription 3 (STAT3)/vascular endothelial growth factor A (VEGFA) pathway in patients with coronary artery disease." (PMID 40563452, 2025). "Supporting angiogenesis is generally regarded as an effective approach for treating ischemic heart disease, and VEGFA promotes angiogenesis after acute MI by increasing reactive oxygen species (ROS) production and enhancing endoplasmic reticulum (ER) stress-mediated autophagy." (PMID 37511521, 2023). "Moreover, VEGFA levels are elevated in the serum and plasma of coronary artery disease (CAD) patients." (PMID 38089766, 2023). "Vascular endothelial growth factor-A (VEGF-A) is one of the polypeptide proteins and the most established factor in the VEGF family as well as prognostic biomarker in coronary heart disease patients." (PMID 36035865, 2022). "ATO at high doses (>0.1 μM) but not low doses reduces not only VEGFA plasma levels in coronary artery disease patients but also basal and LPS-induced VEGFA synthesis in human vascular smooth muscle cells and microvascular endothelial cells." (PMID 34526068, 2021).
lymph node metastasis (129 papers, 1998 to 2026). "Simultaneously, the meta-analysis suggested that increased VEGFA mRNA level was significantly associated with lymph node metastasis (OR=2.12, 95% CI: 1.59-2.82, P=0.188, and I2=31.4%) in ADC patients." (PMID 31892982, 2020). "Importantly, positive expression of TNS4 and VEGFA was significantly associated with lymph node metastasis, and short survival time of ESCC patients, respectively." (PMID 32732965, 2020). "The density of the lymph vessels was manually determined, and the results implied that the high expression level of VEGFA is correlated with lymphangiogenesis and lymph node metastasis." (PMID 24349832, 2013). "In addition, some studies suggested that VEGFA expression has a significant association with EGFR mutations, advanced clinical stage and lymph node metastasis." (PMID 30972298, 2019). "Five genes (VEGFA, IFNB1, IGF1, TEK, and TGFBR1) are associated with angiogenesis, which provides clues to the mechanism of the association between epigenetic inactivation of CYB5R2 and lymph node metastasis." (PMID 26275421, 2015). "Many studies have confirmed that VEGFA is up-regulated in non-small cell lung cancer (NSCLC) tissues and is also significantly positively correlated with lymph node metastasis of NSCLC." (PMID 35928585, 2022). "Patients with lymph node metastasis expressed more VEGFA protein than those without lymph node metastasis (P=0.0299)." (PMID 31892982, 2020). "Previous studies demonstrated that VEGFA/C/D promotes tumor LYM and lymph node metastasis; however VEGFB has not been reported." (PMID 38638428, 2024).